RXRA (retinoid X receptor alpha)
Diseases named in the same sentence as RXRA in open-access papers (continued):
Sharing a sentence is not in itself a finding about the gene and the disease.
cervical carcinoma (6 papers, 2021 to 2025). A carcinoma arising from either the exocervical squamous epithelium or the endocervical glandular epithelium. "LINC00511 contributes to RXRA-mediated transcriptional activation of PLD1 as an oncogenic lncRNA in cervical cancer by recruiting the transcription factor RXRA." (PMID 35771155, 2022). "RXRα is downregulated in cervical cancer and inhibits its progression." (PMID 33968776, 2021). "In contrast, 9-cis-retinoic acid induces NR4A1/RXRα heterodimer formation and NR4A1 and RXRα translocation to mitochondria in human cervical carcinoma cell line HeLa." (PMID 40746844, 2025). "Introduction of siRNAs against LINC00511, RXRA, or PLD1 led to repression of proliferation and promotion of autophagy and apoptosis of cervical cancer cells." (PMID 35456001, 2022). "LINC00511 was shown to bind RXRA, and overexpression of LINC00511 increased PLD1 mRNA and protein expression in cervical cancer cells." (PMID 35456001, 2022). "LINC00511 is upregulated in cervical cancers and could promote PLD1 expression by enriching RXRA to the promoter region of PLD1 and activating PLD1 promoter activity, thus enhancing proliferation and inhibiting the autophagy and apoptosis of cervical cancer cells." (PMID 34803512, 2021).
glioma (6 papers, 2008 to 2024). A benign or malignant brain and spinal cord tumor that arises from glial cells (astrocytes, oligodendrocytes, ependymal cells). "It has recently been shown that FABP7 translocates to the nucleus and interacts with nuclear factors (e.g., ACLY, RXRα) to modulate gene expression associated with cellular physiology and metabolism in both astrocytes and glioma cells." (PMID 39596296, 2024). "The mRNA expression levels of AKT1 and MAPK1 were relatively high in glioma, while those of RXRα, ESR1, and HSP90AA1 were relatively low." (PMID 38835342, 2024). "The analysis revealed that the top five genes affected by isocuB in glioma were RXRα, AKT1, ESR1, MAPK1, and HSP90AA1." (PMID 38835342, 2024). "The potential top five genes of the anti-glioma effect of isocuB were identified by network pharmacology as RXRα, AKT1, ESR1, MAPK1, and HSP90AA1." (PMID 38835342, 2024). "We found that RARA and RXRA protein turnover is blocked in glioma stem-like cells and RARA transcriptional activity is disrupted." (PMID 31700049, 2019). "Furthermore, FABP7 was recently found to interact with nuclear factors, such as ACLY and RXRα, to regulate gene expression in astrocytes and glioma cells, influencing cellular metabolism and proliferation." (PMID 39596296, 2024). "The glioma stem-like cells express high molecular weight forms of RARA and RXRA that fail to be recognized by the proteasome and lack transcriptional activity." (PMID 31700049, 2019). "Glioma cells express sumoylated and high molecular weight RARA and RXRA proteins that have accumulated even before retinoic acid treatment." (PMID 31700049, 2019). "Since PUFAs are natural ligands of RXRα and PPARγ, effects of DHAO or GLAO supplementation on gene expression of these two receptors in rat glioma tumors were explored." (PMID 19014610, 2008). "Therefore, we hypothesize that the inherent resistance to retinoic acid in glioma cells may be due to a block in retinoid receptor degradation pathway that occurs after sumo modification, but before the RARA and RXRA proteins are delivered to the proteasome." (PMID 31700049, 2019).
heart failure (6 papers, 2014 to 2024). Inability of the heart to pump blood at an adequate rate to meet tissue metabolic requirements. "Previous reports showed that RXRA is closely associated with myocardial infarction and serves as a marker for heart failure." (PMID 39546553, 2024). "Understanding the mechanisms underlying the impaired cardiac expression/activation of RARα and RXRα will be important in determining the novel mechanisms leading to heart failure." (PMID 26237391, 2014). "Targeted disruption of RAR and RXR, mainly RARα and RXRα in the embryonic stage, resulted in early postnatal or embryonic lethality and heart failure, suggesting that RARα and RXRα are the two main receptor subtypes that are involved in the regulation of cardiomyocyte differentiation and function." (PMID 26237391, 2014). "It has been reported that decreased cardiac expression of RXRα is involved in the altered myocardial metabolic phenotype in severe heart failure and that downregulation of RXRα may be responsible for impairment in free fatty acid oxidative pathways in the failing heart." (PMID 26237391, 2014).
Hepatic steatosis (6 papers, 2013 to 2024). Steatosis is a term used to denote lipid accumulation within hepatocytes. "In contrast, the ACVR1C gene is linked to “hepatic steatosis”, “glucose metabolism disorder”, and the canonical pathway’s “TGF-b signaling”, “WNT/b-catenin signaling”, and “PPARa/RXRa activation pathway”." (PMID 37511368, 2023). "Furthermore, compared with the control group, hepatic steatosis (fatty liver group) led to decreased mRNA abundance of RXRα, ACO, CPT1, CPT2, LCAD, Nrf1 and TFAM (p < 0.05 or p < 0.01)." (PMID 32230804, 2020). "Sexually-dimorphic expression of the Pnpla3 gene, which is known to be regulated by Srebp1c (but not known to be regulated by RXRα heterodimers) with a polymorphism (I148M) strongly associated with fatty liver disease, has not been reported beforehand." (PMID 23977068, 2013). "miR6262 promoted an extensive inhibition of RXRA and PPARA mRNA levels in basal (untreated with FFA) cells and HepG2 cells exposed to FFA to mimic hepatic steatosis." (PMID 39339747, 2024). "We addressed the potential inhibitory effect of miR6262 on RXRA gene expression and evaluated the impact of miR6262 on key metabolic genes in hepatocytes (HepG2) untreated and exposed to free fatty acids (FFA) to mimic hepatic steatosis, and in brite adipocytes (hMADS cells)." (PMID 39339747, 2024). "In the in vitro model of liver steatosis (HepG2 cells exposed to FFA), the plant miRNA-human target gene bioinformatic prediction was validated, reporting a marked downregulation of the putative target RXRA (−38.05% ± 3.91; p < 0.001) as compared to control cells." (PMID 39339747, 2024).
Hyperglycemia (6 papers, 2016 to 2024). An increased concentration of glucose in the blood. "In summary, the present study demonstrates that in type-1 diabetic kidney, hyperglycemia results in the downregulation of PPARγ and the upregulation of RXRα, RXRβ and RARγ1, which possibly contributes to elevated PAI-1 levels, and thus, elevated MMP-9 and MMP-13." (PMID 34680110, 2021). "Moreover, RXRα signaling protects cardiomyocytes from hyperglycemia by reducing oxidative stress." (PMID 36555577, 2022). "Besides the effects that hyperglycemia could have in CLZ-treated patients with refractory psychosis, we also identified relevant gene enrichment in the thyroid hormone signaling pathway, including the RXRA/RXRG genes." (PMID 33557049, 2021).
steatosis (6 papers, 2021 to 2023). Increased lipid within the cytoplasm of cells. "In HepG2 cells, myclobutanil, mancozeb, and other fungicides such as tributyltin (TBT) induce steatosis also via retinoid X receptor alpha (RXRα), and hepatotoxicity by decreasing the expression of anti-apoptotic markers." (PMID 37242221, 2023). "In addition, this treatment seemed to play the role of metabolic protection being capable to restore the normal level of genes expression upregulated after steatosis treatment, between them RXRA, NR1H2, CEBPB, ADIPOR2, and CYP2E1." (PMID 36770927, 2023). "Feeding mice with ethanol showed a decrease in the levels of RXRα protein, which in turn did not allow binding of PPARα/RXRα to DNA, decreasing mRNA for several genes regulated by PPARα, and therefore, the development of steatosis was favored." (PMID 34361064, 2021).
acute myeloid leukemia (5 papers, 2013 to 2025). Acute myeloid leukemia (AML) is a group of neoplasms arising from precursor cells committed to the myeloid cell-line differentiation. "Preliminary results from our laboratory suggest that NHRs such as PPARG and RXRA were downregulated in chemoresistant acute myeloid leukemia (AML) cell lines, suggesting that NHRs can be modulated to improve chemosensitivity." (PMID 37324449, 2023). "Nrf2 can mediate the 1α,25-dihydroxyvitamin D3-induced differentiation of acute myeloid leukemia cells through multiple mechanisms, including VDR/RXRα transcription." (PMID 23408904, 2013).
esophageal cancer (5 papers, 2005 to 2021). A primary or metastatic malignant neoplasm involving the esophagus. "The expression of RXRα mRNA was lower in oesophageal cancer tissue than that in Barrett's oesophageal tissue in patients with extensive lymph node metastasis." (PMID 33128348, 2020). "Taken together, all these findings suggest that PPARγ is acting as a heterodimer with RXRα to suppress proliferation of esophageal cancer cells." (PMID 27323819, 2016). "Similarly, Hashimoto and colleagues used a combination of 9-cis RA and troglitazone in the same concentrations on the KYSE series of esophageal carcinoma cell lines that all express high levels of RXRα and variable (though present) levels of PPARγ." (PMID 19267912, 2009). "Alterations of retinoic acid receptors (e.g. RARα, β, γ, and RXRα, β, γ) expression is considered to play an important role in development of squamous-cell carcinoma (SCC), which is the most common esophageal cancer." (PMID 16277658, 2005).
gastric cancer (5 papers, 2000 to 2026). A primary or metastatic malignant neoplasm involving the stomach. "Mendelian randomization (MR) analysis was conducted using the TwoSampleMR framework to evaluate the genetic association between RXRA expression and gastric cancer risk, with robustness and sensitivity analyses based on multiple MR methods." (PMID 42063729, 2026). "MR results indicated that genetically predicted increased RXRA expression was significantly associated with elevated gastric cancer risk (OR = 4.216,95%CI:1.201-14.797,P=0.025)." (PMID 42063729, 2026). "In fact, high levels of RARα, RARβ, RXRα and RXRβ are associated with unfavorable prognostic clinical and pathological characteristics of gastric cancer, such as stage-IV and “de novo” metastatic disease." (PMID 39323992, 2024). "The results of the RAR-GASTRIC study demonstrate that gastric cancer specimens contain significant amounts of RARα/RARβ/RXRα/RXRβ mRNAs." (PMID 39323992, 2024). "In this study, we determine the RNA expression of the six isoforms of Retinoic-Acid-Receptors (RARα/RARβ/RARγ/RXRα/RXRβ/RXRγ) in view of their potential use as gastric cancer progression markers and/or therapeutic targets." (PMID 39323992, 2024). "In this single-institution/retrospective clinical and translational study (RAR-GASTRIC), we define the expression of RARα, RARβ, RARγ, RXRα, RXRβ and RXRγ in stomach tumors with the use of archival tissue samples obtained from gastric cancer patients." (PMID 39323992, 2024). "To identify the RAR isoform(s) underlying the anti-proliferative action of the retinoid, initially, we evaluated the constitutive expression of RARα, RARβ, RARγ, RXRα, RXRβ and RXRγ mRNAs in our gastric-cancer cell-lines." (PMID 37951921, 2023). "PPARγ agonists (troglitazone and 15-deoxy-Δ12,14-prostaglandin J2) showed dose-dependent inhibitory effects on the proliferation of the gastric cancer cells, and their effect was augmented by the simultaneous addition of 9-cis retinoic acid, a ligand of RXRα." (PMID 11044367, 2000). "Based on our results, it is reasonable to assume that high expression levels of RARα, RARβ, RXRα and RXRβ have a negative impact on gastric cancer patients’ overall-survival." (PMID 39323992, 2024).
myocardial infarction (5 papers, 2016 to 2024). Gross necrosis of the myocardium, as a result of interruption of the blood supply to the area, as in coronary thrombosis. "However, we show for the first time that reduced Rxrα expression in myeloid cells impacts cardiac remodeling after myocardial infarction and could identify an association with immune dysregulation leading to an increase in infarct size." (PMID 35740296, 2022). "Reduction of Rxrα expression in monocytes and macrophages negatively impacts cardiac remodeling after myocardial infarction as indicated by an increase in infarct size." (PMID 35740296, 2022). "Overall, the reduction of Rxrα levels in monocytes and macrophages negatively impacts cardiac remodeling after myocardial infarction." (PMID 35740296, 2022). "By specifically reducing Rxrα expression in myeloid cells with a tamoxifen-induced Cre-lox-system, we were able to show that a reduction of RXRα levels in monocytes and macrophages negatively impacts cardiac remodeling after myocardial infarction." (PMID 35740296, 2022). "Masson's trichome staining showed that RXRα siRNA significantly increased myocardial infarct size compared to ADSC‐RXRαWT‐FXR treatment (p < 0.05)." (PMID 35780502, 2022). "However, the impact of a reduced Rxrα expression in mononuclear phagocytes on cardiac remodeling after myocardial infarction (MI) has not been investigated to date." (PMID 35740296, 2022).
thyroid cancer (5 papers, 2021 to 2025). "As a fatty acid transporter, FABP3 hypomethylation and consequently overexpression could enhance intracellular lipid flux and activate PPARγ/RXRα signaling, which is implicated in tumor proliferation of thyroid cancer." (PMID 41019337, 2025). "RXRA plays an important role in the occurrence and development of malignant tumors, and its abnormal expression rate in thyroid carcinoma is 66%." (PMID 34840968, 2021).
Cirrhosis (4 papers, 2012 to 2025). A chronic disorder of the liver in which liver tissue becomes scarred and is partially replaced by regenerative nodules and fibrotic tissue resulting in loss of liver function. "Changes in RXRA concentrations have been connected to IL-1, which are proinflammatory cytokines well documented to be elevated within ALD patients and contribute to hepatocyte disfunction leading to fibrosis/cirrhosis." (PMID 39729908, 2025).
colitis (4 papers, 2017 to 2020). Inflammation of the colon. "PPARγ also forms heterodimers with RXRα, and anti-inflammatory effects and amelioration of experimental colitis has been described with a number of PPARγ agonists through trans-repression of signal-dependent transcription factors that mediate inflammatory programs of gene activation." (PMID 28223944, 2017).
COVID-19 (4 papers, 2020 to 2024). A disease caused by infection with severe acute respiratory syndrome coronavirus 2. "Hence the alteration of retinoic acid receptors (RARs), including RARA and related Retinoid X Receptors (RXRs) including RXRA can facilitate COVID-19 pathogenesis which is evident in the published reports." (PMID 38365632, 2024). "In CD14+ monocytes, HIF-1 signaling may regulate LDHA, ALDOA, TIMP1, ELOB and IFNGR2, and PPAR signaling may regulate UBC, RXRA, DBI and ACSL1 in COVID-19 patients." (PMID 33936072, 2021).
liver disease (4 papers, 2013 to 2024). "The nuclear retinoic acid receptors RARβ and RXRα were downregulated in the TGF-β groups in correspondence with previous studies on human liver disease patients." (PMID 39044210, 2024). "Suppression of the PPARα/RXRα pathway by miRNAs may thus promote the progression of liver disease." (PMID 26733244, 2016). "RXRα appears to be one of the most widely distributed transcriptional regulators in mouse liver and is engaged in determining sexually-dimorphic expression of key lipid-processing genes, suggesting novel gender- and gene-specific responses to NR-based treatments for lipid-related liver diseases." (PMID 23977068, 2013). "On the other hand, both RXRA and PANK1 are involved in signaling pathways controlling the metabolism of lipids by hepatocytes, while downregulation may contribute to serious liver disorders, such as NAFLD." (PMID 37894381, 2023).
metastatic tumors (4 papers, 2017 to 2024). "The high levels of RARα, RARβ and RXRα determined in our tumor tissues associated with unfavorable clinical factors such as relapsed and “de novo” metastatic disease." (PMID 39323992, 2024). "The primary and the metastatic tumors shared several important mutations, including in the KMT2D and the RXRA genes." (PMID 30176882, 2018). "The primary and the metastatic tumor have mutations in the KMT2D and RXRA genes." (PMID 30176882, 2018).
osteosarcoma (4 papers, 2020 to 2023). A usually aggressive malignant bone-forming mesenchymal neoplasm, predominantly affecting adolescents and young adults. "Another study on osteosarcomas showed that activation of RXRα and PPARγ may synergistically inhibit tumor growth and cell proliferation, at least partially by inducing osteoblastic differentiation of osteosarcoma cells." (PMID 35406808, 2022). "In “Myeloid”, differentially expressed NRs such as NR4A2, NR4A1, NR3C1, RXRA, NR1D2, PPARD, and RARA were identified among metastasis, primary, and recurrent osteosarcoma tissues." (PMID 35965537, 2022).
cholestasis (3 papers, 2004 to 2025). Impairment of the bile flow caused by obstruction within the liver, or outside the liver in the bile duct system. "Additionally, FXR binds to DNA as a heterodimer with RXRα to transactivate target genes, but RXRα levels are reduced in LPS-induced cholestasis." (PMID 41304731, 2025). "Previous studies by our group demonstrated that inhibition of the JNK signaling pathway completely blocked IL-1β-mediated suppression of RXRα-dependent Ntcp gene expression, thus implicating JNK to be a central player in inflammation-induced cholestasis." (PMID 15312234, 2004).
dementia (3 papers, 2010 to 2023). Loss of intellectual abilities interfering with an individual's social and occupational functions. "To this end, we analyzed LXRβ and RXRα mRNA expression in the hippocampus and inferior temporal gyrus (area 20) of a large series of cases at different stages of dementia and AD associated neuropathology by quantitative PCR." (PMID 20843353, 2010). "Elevated levels of RXRα gene and protein expression have been found in individuals suffering from dementia, and knockout of RXRγ impairs the working memory in mice." (PMID 28815487, 2018). "Although, in the hippocampus, significant increase in RXRα mRNA level was observed in individuals with moderate to severe dementia, significant increase in RXRα protein expression was evident in individuals at an earlier stage of cognitive decline." (PMID 20843353, 2010). "In this work, new evidence is provided from direct analysis of human postmortem brain gene and protein expression suggesting that RXRα, a key regulator of cholesterol metabolism is differentially expressed in individuals with dementia." (PMID 20843353, 2010). "The primary finding was that RXRα levels increased at the very earliest stage of dementia and remained elevated, in general, throughout the course of the disease." (PMID 20843353, 2010).
neuroblastoma (3 papers, 2019 to 2020). Neuroblastoma (NB) is the most common solid, extracranial childhood tumor. "ZNF423 has previously been described as a transcriptional cofactor of RARα/RXRα that is critically required for retinoic acid-induced differentiation of neuroblastoma." (PMID 31234811, 2019). "Among these studies, one study found increased RXRα S22 phosphorylation in human neuroblastoma, which had significantly elevated insulin receptor signalling, and another study detected RXRα S22 phosphorylation in response to insulin in mature 3T3-L1 adipocytes." (PMID 32249683, 2020). "Moreover, ZNF423 was previously reported to act as a co-activator of RARα/RXRα heterodimers in neuroblastoma cells." (PMID 31284679, 2019).